CD74 (CD74 molecule)
Diseases named in the same sentence as CD74 in open-access papers (continued):
Sharing a sentence is not in itself a finding about the gene and the disease.
tumor (continued). "Our findings raise the possibility that tumor-derived MIF could engage CD74 on T cells, thereby disrupting their cytotoxic function and facilitating immune escape." (PMID 41155250, 2025). "Notably, regarding Fib_CD74+–CD4T_FOXP3+ MHC-I ligands (HLA-A/B/C) only exist in normal samples, while in the tumor microenvironment, Fib_CD74+ promotes the recruitment of CD4T_FOXP3+ through the binding of CCL5 to the CCR4 receptor." (PMID 40948762, 2025). "The expression of CD74 in para‐tumour tissue was lower than that in tumour tissue (63.16 ± 3.00 vs." (PMID 40356247, 2025). "Notably, MIF played a crucial role in tumor immune responses through interactions such as MIF - CD74/CD44." (PMID 40036264, 2025). "More in‐depth mechanistic research is required in the future to further explore these dimensions, thereby deepening our understanding of immune regulatory mechanisms within the tumor microenvironment and ultimately validating the therapeutic potential of CD74+ B cells in PSCC." (PMID 41111459, 2025). "Overall, our analysis indicates that tumor cell behaviors are inhibited in the tumor microenvironment of patients with high CD74 expression, while multiple cancer pathways are activated in tumor cells with low CD74 expression." (PMID 40470045, 2025). "MIF exerts its function of promoting leukocyte recruitment to inflammatory sites by noncognate interaction with the chemokine receptors CXCR2 and CXCR4, and regulates the MIF-stimulated survival of macrophages, B cells, and tumor cells through its receptor cluster of differentiation 74 (CD74)." (PMID 39851524, 2025). "Notably, CD74+ B cells within TLSs are pivotal players in immunoregulation that critically shape the tumor immune landscape." (PMID 41111459, 2025). "Studies have shown that in kidney renal clear cell carcinoma, the strong interactions between tumor cells and tumor-associated macrophages, driven by MIF and its receptors CD74 and CD44, are critically involved in tumor progression, angiogenesis, and the mechanism of immune evasion." (PMID 40051627, 2025). "Reduced CD74 expression on neutrophils significantly impairs the anti-tumor function of T cells, whereas high CD74 expression promotes an anti-tumor immune microenvironment and may synergize with immunotherapy to enhance tumor suppression." (PMID 41254689, 2025). "In addition, HCC patients with higher CD74 expression in tumour tissue exhibited a better prognosis in terms of higher OS and lower cumulative recurrence rate." (PMID 40356247, 2025). "Moreover, other studies have indicated that CD74 promotes tumor proliferation and that its expression is negatively correlated with patient survival." (PMID 40470045, 2025). "Interestingly, apCAFs in advanced NSCLC exhibited significantly higher levels of CD74, suggesting variations in their antigen presentation functions across different tumour types." (PMID 38445456, 2024). "Collectively, these results suggest that CD74 may promote tumour proliferation by suppressing CD8+ T cells." (PMID 39113235, 2024). "In both the LN and tumor, colocalization of the CD74, C1QC, and CXCL13 mRNAs was observed." (PMID 39312471, 2024). "Our research indicates that PLOD2 + SAA1 + tumor cells might be capable of communicating with tumor-associated macrophages (TAMs) through specific ligand-receptor pairs, such as MIF-(CD74 + CXCR4), MDK-LRP1 and C3-C3AR1." (PMID 38951896, 2024). "Additionally, MIF released from DKK1+ tumor cells activated CD74, CXCR4, and CD44 on immune clusters." (PMID 39505867, 2024). "Our study utilized SiT, scRNA‐seq, and T‐cell receptor (TCR) analyses of tumor and LN tissues to demonstrate that the temporal heterogeneity of the spatial CD74 isoform correlates with the expanded enrichment of C1QC+ TAMs and CD8+CXCL13+ Tex cells in LN metastasis of ESCC." (PMID 39312471, 2024). "Additionally, similar to Mac_LA, MIF_CD74 appeared to be an important axis ligand involved in cell-cell communication between RTM_Int and tumor cells." (PMID 38972873, 2024).
tumor (continued). "Research on the role of the MIF/CD74 axis in the tumor microenvironment of BM of NSCLC is limited." (PMID 38685050, 2024). "Interestingly, the interaction with the highest probability was observed in the tumor → non-tumor direction for the APP → CD74 interaction." (PMID 39095793, 2024). "However, further investigation is needed into the specific functions of CD74 in individual tumor types." (PMID 38582956, 2024). "Thus, we conducted a comprehensive analysis of the characteristics, clinical relevance, and potential functions of CD74 in tumor immunity, as well as screening for potential activating drugs in pan-cancer." (PMID 38582956, 2024). "Key differences involved enhanced communication in BR1 from the tumor cell cluster enriched in immune and cell-cycle-MPs (T2) to reactive microglia states (Mg9, Mg12–13), including upregulation of the microglia-activating MIF_CD74_CD44 axis." (PMID 39372744, 2024). "Therefore, our research provides a detailed analysis of the multicellular ecosystem in LSCC with COPD, highlighting a significant population of CD74+ tumour cells." (PMID 39113235, 2024). "In addition, SHMT2 is involved in certain processes of tumorigenesis and development and is associated with the expression of MIF, CD74, CXCR4 and CD44 in the HNSCC tumor microenvironment." (PMID 38625586, 2024). "Thus, CD74 can not only directly regulate immune cell activation but also influence tumor progression by regulating tumor cell function." (PMID 39118044, 2024). "In addition to its expression in immune cells, CD74 is overexpressed in various tumor types and can form a complex with MIF, thereby modulating MIF’s function." (PMID 38277205, 2024). "Further, we found that blocking MIF/CD74 axis in vivo could improve the efficacy of radiotherapy and exert anti-tumor effects by inducing microglia polarization toward M1 type after radiotherapy." (PMID 38685050, 2024). "Furthermore, our data indicated a higher proportion of terminally exhausted T cells in CD74‐Over tumour tissues." (PMID 39113235, 2024). "MIF secreted from the tumor cells activates CD74 expressed on DCs." (PMID 39576827, 2024). "Mechanistically, CD74 can shape the tumor microenvironment by regulating the development of myeloid cells, possibly by activating the innate immune response, such as interactions among HPCs, malignant cells, macrophages and DCs, thus facilitating immunotherapy for HCC." (PMID 39118044, 2024). "Our findings indicate that CD74+ tumour cells significantly influence immune responses and could represent a viable therapeutic target in LSCC associated with COPD." (PMID 39113235, 2024). "Cytoplasmic CD74 expressed on APCs functions as an antigen-presenting partner, whereas the overexpression of cell surface CD74 on tumor cells or immune cells serves as MIF receptor, promoting the release of pro-inflammatory and pro-angiogenic factors along with CD44 and CXCR4 ligands." (PMID 38280003, 2024). "The recruitment of GrB+ B cells to tumor tissues occurs through the MIF-(CD74 + CXCR4) axis." (PMID 38386050, 2024). "To assess whether CD74 is expressed in tumor tissues before treatment, we conducted immunohistochemical staining for CD74 in LUAD biopsies obtained from untreated patients." (PMID 39001552, 2024). "The expression of CD74 was elevated in tumor biopsies, similar to that observed in cell lines." (PMID 39001552, 2024). "Notably, the CD74‐202/CD74‐201 ratio in LNs significantly surpassed that observed in the enrichment fraction within the tumor." (PMID 39312471, 2024). "Furthermore, CD74 and CD74+ tumour subsets need to be validated and analysed in larger samples of LSCC with COPD." (PMID 39113235, 2024). "However, in recent study, diversity and plasticity of tumor-associated neutrophil TAN were revealed and HLA-DR+CD74+ neutrophils were positively correlated with the prognosis of several cancer types." (PMID 38962454, 2024).
tumor (continued). "CD74 protein levels were then compared between tumor and normal tissues using the HPA database." (PMID 38582956, 2024). "This study shows that CD74 enhances TBNC growth in mice by inhibiting anti-tumor immunity." (PMID 39576827, 2024). "CD74 expression on tumor cells or total cells has been proved as a favorable prognostic biomarker." (PMID 38280003, 2024). "Gas6 produced by tumor and ependymal cells was predicted to interact with the receptor Mertk in myeloid cells, Tyro3 in tumor cells and Axl in ependymal cells, while additional App-Cd74 signaling axes were predicted between tumor, myeloid, endothelial and ependymal cells." (PMID 38566128, 2024). "MIF released from MMP7+ tumour cells activated CD74, CXCR4 and CD44 on immune clusters." (PMID 39187937, 2024). "Furthermore, its expression was significantly higher on the tumor-infiltrating B cells and DCs compared to its levels on the peripheral splenic populations, suggesting a role for CD74 expressed on these cells in the TNBC ME." (PMID 39576827, 2024). "We speculated that high CD74 expression was attributed to high tumoral infiltration of immune cells, resulting in further efficient HLA antigen presentation and anti-tumor response." (PMID 38280003, 2024). "CD74 expression has also been suggested to serve as a prognostic factor in many of these cancers, with higher relative expression of CD74 behaving as a marker of tumor progression." (PMID 39576827, 2024). "Additionally, we used single-cell RNA sequencing analysis to delineate the immune landscape and tumor heterogeneity in a cohort of HCC patients with high CD74 expression and low CD74 expression." (PMID 39118044, 2024). "CD74 is ectopically expressed in many tumors and can regulate tumor immunity." (PMID 39118044, 2024). "CD74 is implicated in immune cell activation signaling, playing a pivotal role in histocompatibility complex II (MHCII)-restricted antigen presentation and anti-tumor immunity." (PMID 38472225, 2024). "In cancer, MIF/CD74 axis is considered to be a signaling pathway that pro-tumor." (PMID 38685050, 2024). "However, while the CD74‐201 isoform was detected in both LN and tumor samples, the CD74‐202 isoform remained undetected in the tumor sample." (PMID 39312471, 2024). "In addition to its effect on immune cells, the inhibition or knockout of CD74 can significantly inhibit the proliferation and invasion of tumor cells in many solid tumors." (PMID 39118044, 2024). "To determine whether CD74 plays a role in the functionality of the tumor-infiltrating immune cells, we first analyzed its expression on these cells." (PMID 39576827, 2024). "Interestingly, a heterogeneous staining pattern among the tumor cells was observed in the tumor mass, implying that some tumor cells expressed higher levels of CD74." (PMID 39001552, 2024). "Taken together, our results demonstrated that AK104 could efficiently improve tumor immune microenvironment, and CD74 could serve as a predictive biomarker." (PMID 38280003, 2024). "CD74 is predominantly expressed in the cytoplasm and membrane of immune cells and tumor cells." (PMID 38280003, 2024). "In total, five populations were designated tumour clusters, which had various features: (TumourC0) CD74 and APOD; (TumourC1) IF16, JUN and HSPA1A; (TumourC2) S100B and SCRG1; (TumourC3) NEAT1 and MALAT1; and (TumourC4) WFDC2 and RNASE1 (HLA‐DRA, CD68, CD3D, CD3E)." (PMID 37784253, 2023). "The CD74 expression in tumor tissues was greatly elevated compared to that in normal tissues." (PMID 37629174, 2023). "We also noticed that MHCII molecule including HLA-DPA1, HLA-DRB1, HLA-DQA1 and CD74 were significantly downregulated in this cluster of macrophages, which may contribute to sub-optimal tumor antigen presentation." (PMID 37957625, 2023). "The present study was the first to propose that high CD74 expression may be derived from tumor-infiltrating immune cells." (PMID 36911401, 2023).
tumor (continued). "Similarly, niche indications for ADCs in clinical development included targets for CD71, PSMA, PTK7 or CD74, in tumours like breast, lung, stomach or colon." (PMID 37740463, 2023). "Further, we detected several genes that were both mutated and differentially spliced in the same cell types, such as HMGN3 and UBE2G2 in tumor cells, CD74 and IFI30 in myeloid cells, and RPS2 in endothelial cells indicating their important roles in tumorigenicity." (PMID 37433798, 2023). "Similarly, CD74-positive macrophages have been found to promote tumor growth in a mouse model of undifferentiated pleomorphic sarcoma." (PMID 36508875, 2023). "Notably, heterogeneity of CD74 expression has been confirmed in tumor tissues, indicating that characterization of immune landscape cannot be discounted." (PMID 36911401, 2023). "Studies have shown that CD74 promotes tumour cell growth by interacting with MIF." (PMID 36860314, 2023). "However, the expression of genes participating in AP (e.g., HLA‐DRA/DMB and CD74) and anti‐tumour immunity (e.g., GBP1, IFNG and TNFRSF9) were significantly higher in the TS, while genes involved in angiogenesis (e.g., VEGFA) was significantly higher in TN." (PMID 37491740, 2023). "CD33 is widely used as a marker for tumor infiltrating myeloid cells, so we collected FFPEs from 28 consecutive pairs of BC patients and performed IHC for CD74 and CD33, respectively." (PMID 36911401, 2023). "Through the indirect co-culture of fibroblasts and tumor cells, we demonstrated that the CD74-mediated secretions of S100A8/A9 could induce oncogenic expressions of cytokines in NFs." (PMID 37629174, 2023). "Lastly, we demonstrate that CD74 knockdown reduces tumor growth in vivo." (PMID 37629174, 2023). "Besides, MIF-(CD74+CXCR4) and MIF-(CD74+CD44) pathways were widespread and are associated with multiple cell types in the tumor and normal tissues." (PMID 37335089, 2023). "Of note, we observed that ascites-enriched RTMs expressed lower levels of CD74 and HLA-II related genes than monocyte-derived AeMs, contrary to the observations of TeMs, likely reflecting the different ontogeny of RTMs in ascites and tumor tissues." (PMID 37488416, 2023). "Additionally, CD74 can also participate in signal transduction pathways and is considered a prognostic factor in cancer, as higher expression of CD74 indicates tumor progression." (PMID 38099290, 2023). "By performing a differential analysis between the two tumor cell compartments, we found that numerous genes associated with antigen presentation (e.g., HLA-DRA, CD74) were intensively upregulated in APHC, while a variety of metabolic enzymes (e.g., CYP3A5, ALDOB) were highly expressed in ANHC." (PMID 37336873, 2023). "CD74 has been reported to promote tumor cell growth through interaction with MIF." (PMID 35169832, 2022). "Also, CD74 promotes tumor cell survival by interacting with macrophage migration inhibitory factor (MIF)." (PMID 35784460, 2022). "Other studies have also found CD74 is expressed in BC circulating tumor cells." (PMID 36226063, 2022). "In this context, CD74+ macrophage/microglia infiltration is increased in BM while CD74 in the nucleus acts as a transcription factor and induces the expression of midkine, a pro-tumorigenic molecule stimulating tumor growth." (PMID 35884845, 2022). "CD74 levels have been found to be linked with improved prognosis in invasive basal-like BC, possibly due to raised MHCII levels in tumor cells and greater numbers of tumor-infiltrating lymphocytes." (PMID 36226063, 2022). "We found strong interactions between tumor cells and TAM populations mediated by macrophage migration inhibitory factor (MIF) and its receptors (CD44 and CD74), which have been well characterized to play vital roles in tumor progression, angiogenesis, and immune escape in ccRCC70–72." (PMID 35853872, 2022).
tumor (continued). "Furthermore, MIF promotes tumor proliferation, migration, invasion, angiogenesis and chemotherapy resistance via binding to different receptors, including CD74, C-X-C motif chemokine receptor 2 (CXCR2), CXCR4, and CXCR7." (PMID 35842634, 2022). "Mechanistically, overexpression of MIF in NSCLC increases the phosphorylation level of JNK, c-Jun, and subsequent activity of the transcription factor AP-1 in a CD74-dependent manner, which promotes tumor angiogenesis by increasing expression of the angiogenic factors CXCL8 and VEGF." (PMID 35842634, 2022). "CD74 tumor cell expression in clinical samples of brain metastases was here also associated with better overall survival, which indicates that indeed the MHC class II-related functions of CD74 are also important in the context of cancer." (PMID 34944801, 2021). "In cancers, many studies have demonstrated that CD74 is overexpressed in tumor cells." (PMID 34944801, 2021). "As expected, we found reactivity for CD74 in both tumor cells and in stromal components." (PMID 34944801, 2021). "The activation of CD74 inhibits microglial migration and therefore, invasion into the tumor." (PMID 34571885, 2021). "In contrast, we have shown that in BM tissue loss of CD74, there is a strong negative prognostic marker with the expression regulated by promoter methylation and negatively associated with tumor-infiltrating T-lymphocytes (TILs)." (PMID 34209696, 2021). "The importance of antigen presentation in immune-oasis SCLC is further supported by MHCII-related molecules, such as HLA-B, TAP1, and CD74, which are all extensively overexpressed in this tumor phenotype and strongly interconnected according to string maps and network analysis." (PMID 34200100, 2021). "Cd74 is found overexpressed in several types of cancers, suggesting that Cd74 may serve as a tumor progression marker." (PMID 34836197, 2021). "Notably, MIF has been reported to be overexpressed in several cancers, and the interaction between MIF and CD74 has also been shown to promote cell proliferation and tumor growth." (PMID 34805184, 2021). "Here, gene expression analyses using macro-dissected tumor tissues (cDNA microarray and RT-qPCR) revealed consistent CD74 decreased expression, whereas the IHC analysis showed moderate to strong immunopositivity in endothelial and inflammatory cells in most JNA samples." (PMID 34572445, 2021). "Since the high immune infiltration indicated low tumor purity, the negative correlation between CD74 and tumor purity suggested that high expression of CD74 was associated with high immune infiltration." (PMID 34540893, 2021). "Moreover, supra-transfecting MHC class II+ tumor cells with li gene, coding for li protein (CD74), the invariant chain that normally blocks the binding of self-peptide fragments to MHC class II molecules, abrogated the immunogenicity of the modified cells." (PMID 32079263, 2020). "Here we found that the receptor CD74 may play a greater role in GBM MDSC biology because the subset of MDSCs primarily found in the tumor microenvironment were M-MDSCs, which predominantly express CD74 as a MIF receptor." (PMID 32625208, 2020). "Strikingly, for genes in cluster ii), which are specifically up-regulated in AAS, high expression of 7 of the top 10 genes (C3, CD74, HLA-DRA, STRA6, IGFBP4, PIGR, and TNIP1) was strongly associated with better cumulative survival than tumours with low expression of these genes." (PMID 32218455, 2020). "In cases where a sufficiently strong anti-tumor response cannot be induced by the antigens presented by HLA-DR, the co-expression of receptors such as CD74 that promote tumor cell survival may dominate the result." (PMID 32934776, 2020). "Some of those might be expressed by both tumor cells and immune cells, such as CD74, and represent potential therapeutic targets for immunomodulation." (PMID 33228231, 2020). "CD74 is significantly high and might prevent the presentation of tumour antigens in various tumour cells." (PMID 33113804, 2020).